TRPV2 (transient receptor potential cation channel subfamily V member 2)
Description:
Calcium-permeable, non-selective cation channel. Seems to be regulated, at least in part, by growth factors, such as IGF1, PDGF and morphogenetic neuropeptide/head activator. May transduce physical stimuli in mast cells (By similarity).
Synonyms: VRL-1; VRL; VRL1
Tractability: Small molecule: it belongs to a druggable protein family. Antibody: its Gene Ontology location is reachable by antibodies, with high confidence; UniProt places it where antibodies can reach, with medium confidence; UniProt predicts a signal peptide or a membrane-spanning region; the Human Protein Atlas places it where antibodies can reach. PROTAC: ubiquitination databases record sites on it; its protein half-life has been measured; a small molecule that binds it is known.
Target class: Voltage-gated ion channel; Ion channel; Transient receptor potential channel
Gene: Protein-coding gene on chromosome 17 (16,415,571 to 16,437,003, forward strand). Ensembl gene ENSG00000187688.
Subcellular location: Cell membrane; Cytoplasm; Melanosome
Subcellular location (Human Protein Atlas): Plasma membrane
Pathways (Reactome):
Transport of small molecules: TRP channels
Gene Ontology:
Molecular function: monoatomic cation channel activity; protein binding; calcium channel activity; monoatomic ion channel activity; monoatomic ion transmembrane transporter activity
Biological process: response to temperature stimulus; calcium ion import across plasma membrane; calcium ion transmembrane transport; positive regulation of cold-induced thermogenesis; sensory perception; monoatomic ion transport; positive regulation of axon extension; positive regulation of calcium ion import; transmembrane transport
Cellular component: plasma membrane; axon; axonal growth cone; cell body; cell surface; cytoplasm; growth cone membrane; melanosome; membrane
Genetic constraint (gnomAD): Loss-of-function variants: 58 observed, 92 expected, observed/expected ratio (o/e) 0.63, 90% interval 0.51 to 0.79. The upper end of that interval is the gene's LOEUF score, 0.79, which puts it in group 3 of 6, group 1 being the genes least tolerant of losing a copy. Missense variants: 807 observed, 999.06 expected, observed/expected ratio (o/e) 0.81, 90% interval 0.76 to 0.86. Synonymous variants: 417 observed, 428.65 expected, observed/expected ratio (o/e) 0.97, 90% interval 0.9 to 1.05.
Homologues: Orthologues: chimpanzee TRPV2 (99% identical), macaque TRPV2 (95% identical), dog TRPV2 (84% identical), rabbit TRPV2 (84% identical), mouse Trpv2 (81% identical), rat Trpv2 (78% identical), pig TRPV2 (78% identical), guinea pig TRPV2 (75% identical), tropical clawed frog trpv2 (48% identical), zebrafish trpv1 (43% identical), Caenorhabditis elegans ocr-4 (22% identical), Drosophila melanogaster nan (21% identical), and 2 more. Paralogues in human: TRPV1 (45% identical), TRPV4 (42% identical), TRPV3 (37% identical), TRPV6 (24% identical), TRPV5 (24% identical).
Diseases named in the same sentence as TRPV2 in open-access papers:
TRPV2 is named in the same sentence as 158 diseases in open-access papers, as found by Europe PMC text mining. Sharing a sentence is not in itself a finding about the gene and the disease. The quoted sentences say what the papers report.
glioma (31 papers, 2014 to 2026). A benign or malignant brain and spinal cord tumor that arises from glial cells (astrocytes, oligodendrocytes, ependymal cells). "Univariate COX regression analysis demonstrated that most TRPGs and TRPV2 were prognostic risk factors for gliomas." (PMID 38948951, 2024). "In cancers, the overexpression of TRPV2 was associated with increased survival of patients with hepatocellular carcinoma, glioma and glioblastoma, while the opposite was seen for esophageal squamous cell carcinoma, urothelial carcinoma, prostate, breast and gastric cancer." (PMID 36744297, 2023). "Moreover, they found that TRPV2 silencing was associated with ERK activation that drives glioma cell proliferation and apoptosis evasion by Fas and PI3K/Akt repression and Bcl-xL expression." (PMID 31083561, 2019). "Thus, loss or alterations of TRPV2 expression in cancer cells results in an impairment of these processes, as shown in prostate tumor-derived endothelial cells and gliomas." (PMID 33928077, 2021). "TRP channels consist of seven subfamilies, with TRPV2 being a key member that significantly impacts glioma cell development." (PMID 40535121, 2025). "Another study by Nabissi and colleagues (2013) propose that CBD increases TRPV2 expression and activity, increasing chemotherapeutic drug uptake and inducing apoptosis of glioma cells." (PMID 40002932, 2025). "Activating TRPV2 channels enhances macrophage migration towards tumor cells within the glioma microenvironment, thereby inhibiting tumor cell proliferation." (PMID 40535121, 2025). "We also performed IHC staining of 56 glioma tissues to confirm the correlation between the levels of TRPV2 and the macrophages." (PMID 38948951, 2024). "Activation of TRPV2 channels can negatively regulate glioma cell survival and proliferation, while also promoting the differentiation of glioma stem cells." (PMID 38987805, 2024). "TRPV2 was demonstrated to promote macrophage migration toward malignant cells and improve glioma prognosis in in vitro and in vivo experiments." (PMID 38948951, 2024). "Reducing the expression of TRPV2 with siRNA knockdown enhanced the proliferation of U87MG glioma cells indicating TRPV2 negatively controls glioma proliferation." (PMID 36768856, 2023). "The CBD-induced TRPV2-dependent autophagic process stimulated glioma stem-like cells in a PI3K/Akt signaling-dependent manner." (PMID 35628181, 2022). "In contrast, TRPV2 upregulation in MZC primary glioma cells, by inducing Fas overexpression led to reduced viability and increased spontaneous as well as Fas-induced apoptosis." (PMID 33928077, 2021). "First, TRPV1 and TRPV2 genes and protein expression appeared inversely correlated with glioma grade, showing an almost undetectable level in GBM." (PMID 33928077, 2021). "In gliomas, it has been shown that TRPV2 reduced cell proliferation and increased cell sensitivity to Fas-induced apoptosis in an ERK-dependent manner." (PMID 33928077, 2021). "TRPV2 exerts its anti-tumorigenic function on gliomas through the regulation of several signaling pathways involved in cell proliferation and survival, stem cell differentiation and sensitivity to drugs." (PMID 33928077, 2021). "More specifically, TRPV1 and TRPV2 have revealed a protective role in glioma cells by regulating cell proliferation and survival, stem cell differentiation and sensitivity to drugs, whereas TRPV4 was found to increase cancer cell invasiveness." (PMID 33928077, 2021). "TRPV2 expression decreases during glioma progression to higher clinical stages; TRPV2 negatively controls glioma cell survival and proliferation and protects cells from Fas-induced apoptosis in an ERK-dependent manner." (PMID 34458247, 2021). "The pore region of TRPV2, critical for its Ca2+ activity, was required for boosting glioma chemosensitivity to cytotoxic drugs." (PMID 33376561, 2020).
glioma (continued). "In further experiments, TRPV2–PCNH efficiently accumulated on TRPV2-transfected C6 glioma cells and led to Ca2+ influx following NIR laser irradiation." (PMID 32807785, 2020). "In contrast, silencing TRPV2 in the glioma cell line U87MG was found to increase resistance to apoptotic cell death and promotes cell proliferation and survival." (PMID 30733502, 2019). "The pore region of TRPV2 has been demonstrated to be critical for ion channel permeation and the resulting increase of glioma chemosensitivity and cytotoxic effects." (PMID 30845786, 2019). "CBD, through TRPV2 activation, stimulates autophagy in glioma stem-like cells, promoting cell differentiation, and increasing the sensitivity to BCNU- and TMZ-mediated apoptosis." (PMID 31801263, 2019). "The TRPV2 interactome showed a high association with early glia-related neoplasms, especially glioma/glioblastoma, being ABR, FGF1, KCNJ10, PEBP1, PLP1, SDC3, and TRPV2, the genes associated to these brain neoplasms." (PMID 29719613, 2018). "Since the chemotherapeutic drugs used in this study have a molecular weight lower than DOXO (DOXO MW: 580; TMZ MW: 194; BCNU MW: 214), it suggested that TRPV2 channels can also mediate their uptake in glioma cells." (PMID 24709905, 2014). "By using natural red fluorescent Doxorubicin (DOXO), we showed that its uptake is markedly increased in TRPV2 overexpressing MZC glioma cells." (PMID 24709905, 2014). "In this regard, we have provided evidence of the expression of TRPV2 by glioma cells and tissues and its involvement in ERK-dependent regulation of glioma cell proliferation and susceptibility to Fas-induced apoptosis." (PMID 24709905, 2014). "Glioma cells expressing this mutant TRPV2 channel showed an inhibition of TRPV2-induced cytotoxic effects and reduced DOXO uptake." (PMID 24709905, 2014). "Moreover, Probenecidsol can activate TRPV2 channels, although further research is required to confirm its efficacy in inhibiting tumor cell proliferation in glioma through this mechanism." (PMID 40535121, 2025). "TRPV2 activation could promote macrophages migration toward malignant cells and alleviate glioma prognosis." (PMID 38948951, 2024). "We co‐cultured glioma cells and macrophages in vitro and found that probenecid (a TRPV2 agonist) could promote the migration of macrophages to malignant cells." (PMID 38948951, 2024). "In addition to normal tissues, TRPV2 is expressed in various tumor cells, including gliomas, glioblastoma, and hepatoma cells." (PMID 39334351, 2024). "In addition, the CBD-induced TRPV2-dependent autophagic process induces glioma stemlike cells in a PI3K/Akt signaling-dependent manner." (PMID 35628181, 2022). "In adult glioma patients, TRPV2 expression increases during GSC differentiation." (PMID 35887116, 2022). "TRPV2 is present in glioma and GSCs isolated from adult patients." (PMID 35887116, 2022). "In vitro, cannabidiol inhibits migration and induces apoptosis in human glioma cells, while it increases chemotherapeutic drug uptake and parallelly potentiates the cytotoxic activity of chemotherapeutic agents in a TRPV2-dependent manner in human glioma cells." (PMID 34458247, 2021). "Interestingly, CBD was also evidenced to promote glial differentiation in glioma stem-like cells (GSCs) via a TRPV2-dependent manner." (PMID 33806707, 2021). "The scientific literature reports the implications of TRPV1 and TRPV2 in glioma cell biology." (PMID 34458247, 2021). "Similarly, TRPV2 silencing promotes glioma cell survival and proliferation and resistance to Fas-induced apoptotic cell death in an ERK-dependent manner." (PMID 34671260, 2021). "Moreover, TRPV2 has been shown to promote, both in vitro and in vivo, differentiation of glioma stem-like cells, leading to a decreased proliferation rate." (PMID 31801263, 2019). "In addition, enforced TRPV2 expression on low TRPV2-expressing MZC glioma cells resulted in a marked inhibition of cell survival and enhanced spontaneous apoptosis." (PMID 24709905, 2014).
glioma (continued). "Moreover, we conducted in vitro and in vivo experiments to demonstrate that TRPV2 activation could promote macrophage migration toward malignant cells, and improve glioma prognosis." (PMID 38948951, 2024). "Therefore, we aimed to investigate the immunological implications of TRPV2 in gliomas." (PMID 38948951, 2024). "In addition to TRPV1, TRPV2 plays a role in regulating glioma cell survival and proliferation, with high levels of TRPV2 expression detected in benign astrocytes, with progressively less expression of TRPV2 in high-grade gliomas corresponding with histological grade." (PMID 32340151, 2020). "Moreover, overexpression of TRPV2 in MZC glioma cells induces spontaneous chemoresistance." (PMID 32575381, 2020). "The antitumor effects of CBD appear to be mediated by transient receptor potential cation channels (TRPVs) in endometrial cancer, glioma, bladder cancer, and myeloma, with TRPV1, TRPV2, and TRPV4 playing key roles in activating apoptosis." (PMID 40006844, 2025). "Nabissi and colleagues identified the downregulation of TRPV2 in high-grade gliomas as well as in U87MG cells and in MZC, FCL, and FSL primary glioma cells." (PMID 36768856, 2023). "There is a growing consensus that TRPV1, TRPV2, TRPM2, TRPM3, and TRML1 exert anti-tumorigenic properties in glioma, while TRPC1, TRPC6, TRPM7, TRPM8, and TRPML2 promote glioma growth and proliferation." (PMID 36768856, 2023). "CBD at higher concentration (30 μM) induced cell death in human T24 bladder cancer cells through activating TRPV2, and CBD decreased glioma stem-like cell viability with an IC50 of nearly 20 μM in a TRPV2-dependent manner." (PMID 33806707, 2021). "Cannabidiol, by activating TRPV2, (i) triggers GSC differentiation, (ii) activates their autophagic processes, (iii) inhibits glioma stem cell proliferation, (iv) inhibits their clonogenic capability, and (v) abrogates their resistance to carmustine (BCNU)." (PMID 34458247, 2021). "Moreover, glioma cell proliferation is inhibited by cannabidiol-induced TRPV2 activation, resulting from TRPV2-dependent Ca2+ influx and increase in the uptake of cancer chemotherapeutic drug, which, in parallel, potentiates cytotoxic activity in human glioma cells." (PMID 32963700, 2020). "The activation of TRPV1 by CBD, and of TRPV2 by CBD and ∆9-THC, inhibits human glioma cell proliferation and viability in vitro." (PMID 32340151, 2020). "Conversely, reduced TRPV2 expression has been detected in advanced glioma, therefore its exogenous overexpression negatively affected the in vitro and in vivo proliferation of glioma cells, indicating that in different cancers, TRPV2 may function either as a tumour promoter or tumour suppressor." (PMID 32575381, 2020). "A recent study demonstrated that the TRPV2 agonist CBD was able to enhance TRPV2 expression and activation leading to an increased chemosensitivity of glioma cells." (PMID 24709905, 2014). "CBDis a well-tolerated, nonpsychoactive phytocannabinoid thatexhibits antitumor activity against GBM and glioma stem-like cells.This is achieved through mechanisms such as inducing oxidative stress,activating caspases, modulating ERK and TRPV2/TRPV4 signaling, andsuppressing NF-κB and Id1." (PMID 41288593, 2026). "Notably, we observed among the articles included in this study that CBD was able to interact mainly with TRPVS receptors, as in endometrial cancer (TRPV1), glioma (TRPV2 and TRPV4), bladder cancer (TRPV2), and myeloma (TRPV)." (PMID 40006844, 2025). "Conversely to TRPV1 and TRPV2, TRPV4 has revealed a pivotal role in promoting glioma progression." (PMID 33928077, 2021). "Specifically, by using the natural red fluorescent DOXO, it has been demonstrated that TRPV2 overexpression in MZC glioma cells markedly increased DOXO uptake in a Ca2+-dependent manner, since Ca2+ chelation by EGTA completely inhibited the CBD-induced TRPV2-mediated increase of DOXO-positive cells." (PMID 33928077, 2021).
glioma (continued). "Similarly, TRPV2 activation enhances the cytotoxic effects of temozolomide (TMZ), carmustine (BCNU), and doxorubicin in U87MG and MZC glioma cell lines." (PMID 32575381, 2020). "TRPV2 was found to be expressed in benign astrocyte tissues, in glioma cell lines and in glioma tissues, with a marked reduction of TRPV2 in high-grade gliomas, suggesting that TRPV2 expression played a negative role in tumor progression." (PMID 24709905, 2014). "For example, CBD’s effects in glioma are dependent on TRPV2, but not on CB1, CB2, and TRPV1." (PMID 33143283, 2020).
prostate carcinoma (24 papers, 2013 to 2025). A carcinoma that arises from epithelial cells of the prostate gland. "TRPV2 overexpression has been linked to cell proliferation, migration, and survival in some cancer including breast cancer prostate cancer, esophageal squamous cell carcinoma." (PMID 40936093, 2025). "In prostate carcinoma, TRPV2 expression has been associated with the aggressive, castration-resistant phenotype." (PMID 37240443, 2023). "In prostate cancer, TRPV2 overexpression was associated with the castration-resistant phenotype and metastasis." (PMID 33376561, 2020). "These have been reported to be implicated in tumourigenesis, and more specifically, the TRPV2 channel has been found to promote the progression of prostate cancer towards a more aggressive phenotype by stimulating migration and invasion in cells." (PMID 28845385, 2017). "Likewise, in prostate cancer, TRPV2 is overexpressed and linked to the castration-resistant phenotype and metastasis." (PMID 39334351, 2024). "Subsequently, increased TRPV2 expression was also observed in other malignancies like breast cancer, esophageal squamous cell carcinoma, gastric cancer, urothelial cancer and prostate cancer." (PMID 34936030, 2021). "For example, an increase in the expression of the Ca2+ channels TRPV2 in prostate cancer, and TRPM8 in squamous cell carcinoma resulted in induction of MMP-2 and MMP-9, respectively." (PMID 33802790, 2021). "In conclusion, these studies indicate TRPV2 to be a promising target to treat prostate cancer and metastasis." (PMID 33376561, 2020). "Over-expression of TRPV2 in androgen-dependent LNCaP prostate cancer cells led to the induction of invasive markers, matrix metalloproteinases (MMP9) and cathepsin-B." (PMID 32825277, 2020). "TRPV2 is overexpressed by a variety of cancer cells and plays a functional role in hepatocellular carcinoma, prostate cancer, bladder cancer, and glioblastoma development." (PMID 31680972, 2019). "It has been reported that TRPV2 is activated by the lysophospholipids, lysophosphatidylcholine and lysophosphatidylinositol, and TRPV2-knockdown in the prostate cancer cell line PC3 decreases lysophospholipid-induced migration." (PMID 31275168, 2019). "AM can induce a metastatic phenotype in prostate cancer cells through its action on TRPV2 calcium channels and is also capable of influencing localised levels of RANKL in the bone to favour tumourigenesis." (PMID 28845385, 2017). "TRPV2 has been demonstrated to facilitate the growth of prostate cancer cells and their invasive properties." (PMID 28264681, 2017). "siRNA knockdown of TRPV2 in these cells abolishes all effects seen by AM treatment leading to the conclusion that this Ca2+ channel is regulated by AM and helps to promote prostate cancer cells to require a metastatic phenotype [25•]." (PMID 28845385, 2017). "Meanwhile, TRPV2 was higher in prostate cancer with metastatic cancer (stage M1) relative to primary solid tumors (stages T2a and T2b)." (PMID 28264681, 2017). "On the other hand, in prostate cancer cells, Ca2+-dependent activation of TRPV2 induced by lysophospholipids increases the invasion of tumor cells." (PMID 24709905, 2014). "The constitutive activity of TRPV2 is also critical for castration-resistant prostate cancer development and progression in vivo." (PMID 24709905, 2014). "In the present work we investigated the involvement of TRPV2 in the effect of AM on the multistep process of invasion in two highly invasive cell lines: the PCa (Prostate Cancer) cells PC-3 and the UC (Urothelial Carcinoma) cells T24/83." (PMID 23741410, 2013). "The Transient Receptor Potential channel TRPV2 is known to promote in prostate cancer cell migration and invasive phenotype and is correlated with the stage and grade of bladder cancer." (PMID 23741410, 2013).